ABCA1 (ATP binding cassette subfamily A member 1)
Diseases named in the same sentence as ABCA1 in open-access papers (continued):
Sharing a sentence is not in itself a finding about the gene and the disease.
atherosclerosis (continued). "In addition, it has been reported that the absence of ABCA1 expression causes the intracellular accumulation of cholesterol and facilitates the progression of atherosclerosis." (PMID 37754229, 2023). "Among them, ABCA1 and ABCG1 are the main players in mediating cholesterol efflux, as suggested by the fact that genetic mutations of ABCA1 lead to the Tangier disease, a genetic disorder characterized by cholesterol accumulation in various organs, atherosclerosis and premature coronaropathy." (PMID 36830593, 2023). "Clinical studies have shown that carriers of ABCA1 functional loss mutations are characterized by reduced levels of high-density lipoprotein cholesterol, which is found in tissues rich in macrophages and reticular endothelial cells, leading to atherosclerosis." (PMID 37322486, 2023). "Similarly, the RCT effect on reducing atherosclerosis in mice was proven via bone marrow transplantation studies using wild-type or ABCA1-deficient donors." (PMID 35052806, 2022). "Mutation of ABCA1 in apoE–/– mice has little effect on atherosclerosis." (PMID 35498045, 2022). "Moreover, the different underlying mechanisms of ABCA1 and atherosclerosis have been illustrated in many studies." (PMID 35743794, 2022). "Studies from our group and others have demonstrated that astragalin, C1q tumor necrosis factor-related protein 12, fargesin and biochanin A increase RCT efficiency and protect against atherosclerosis in apolipoprotein E-deficient (apoE−/−) mice by up-regulating ABCA1 and ABCG1 expression." (PMID 35902881, 2022). "Mice doubly deficient in Abca1 and Abcg1 exhibit worsened atherosclerosis." (PMID 35714730, 2022). "The level of miR-33a is increased and accompanied by a decreased level of ABCA1 in monocytes of patients with hypertension, in the plasma of patients with untreated hyperlipidemia, who have an increased risk of atherosclerosis, and in abdominal aortic aneurysm tissues." (PMID 34940525, 2021). "Furthermore, LDL receptor knockout mice that received bone marrow from mice deficient in ABCA1 and SR-B1 exhibited a noticeable increase in the extent of atherosclerosis as compared to ABCA1 deficiency bone marrow in LDL receptor knockout recipient mice." (PMID 34072125, 2021). "Therefore, a better understanding of the molecular mechanisms underlying ABCA1 regulation is of critical importance to develop novel therapeutic strategies for atherosclerosis." (PMID 33293505, 2020). "Interestingly, we previously showed that uninephrectomy-induced amplification of murine atherosclerosis is linked to impaired cholesterol efflux reflecting repression of macrophage ATP-binding cassette transporter A1 (ABCA1)." (PMID 29374468, 2018). "Westerterp et al72 demonstrate that deficiency of ABCA1/ABCG1 in endothelial cells accelerates atherosclerosis, and they suggested that endothelial cell–derived ABCA1/ABCG1 plays a role in preservation of endothelial NO synthase activity and suppression of endothelial inflammation." (PMID 29437605, 2018). "Moreover, impairment in ABCA1-driven cholesterol efflux is associated with increased arterial-wall thickness and atherosclerosis in humans, indicating the important role of cholesterol efflux in the process of AS." (PMID 29137283, 2017). "They concluded that impaired ABCA1-mediated cholesterol export could contribute to the increased atherosclerosis and nephropathy associated with diabetes." (PMID 26788366, 2015).
atherosclerosis (continued). "Leukocyte ABCA1 deficiency, as well as splenectomy independently induce atherosclerotic lesion development, demonstrating the particular importance of both leukocyte ABCA1 and the spleen with respect to atherosclerosis." (PMID 23133551, 2012). "Because ABCA1 has many functions in distinct cell types, these discrepancies may be due to a pleiotropic effect of ABCA1 variants in other cell types involved in the pathophysiology of atherosclerosis and CAD." (PMID 23152888, 2012). "That ABCA1 does indeed have a significant atheroprotective role in vivo is further supported by a recent study from the Hayden laboratory, which reported tissue-specific roles of ABCA1 that influence atherosclerosis susceptibility." (PMID 19718435, 2009). "The ABCA1 gene is involved in the regulation of cholesterol transport and phospholipid balance in cells, while the rs2230806 polymorphism leads to downregulation of gene activity, playing a significant role in the development of atherosclerosis and other age-related diseases." (PMID 41226793, 2025). "In addition to Tangier disease, variations and changes in the ABCA1 gene increase the risk of atherosclerosis, familial hypercholesterolemia, coronary heart disease, including myocardial infarction and ischemic stroke, and can be considered as a prognostic biomarker." (PMID 36011386, 2022). "MeXis knockout mice exhibited a reduction of Abca1 expression, and a loss-of-function of MeXis in mouse bone marrow cells altered chromosome architecture at the Abca1 locus, impaired macrophage cholesterol efflux, and accelerated the development of atherosclerosis." (PMID 32765426, 2020). "In addition, by using a murine model of atherosclerosis, it was shown that myeloid Abca1/g1 deficiency enhanced caspase-1 activation in monocytes, macrophages, and neutrophils, resulting in enhanced atherogenesis that was suppressed by Nlrp3 or Caspase-1/11 deficiency." (PMID 31374929, 2019). "Downregulation of ABCA1 in senescent macrophages disrupts the cell’s ability to remove cholesterol from its cytoplasm, leading the cells to promote the pathologic atherogenesis which plays a central role in common age-associated diseases such as atherosclerosis and AMD." (PMID 29534722, 2018). "HIV, via the viral accessory protein Nef, stimulates the degradation of ATP-binding cassette transporter A1 (ABCA1) and impairs cholesterol efflux from macrophages, causing accumulation of cholesterol and the transformation of macrophages into foam cells, a hallmark of atherosclerosis." (PMID 26005590, 2014). "Thus, a deficiency in the ability of apoE4 to induce macrophage ABCA1 expression and apoAI-mediated cholesterol efflux might contribute to the pathogenesis of atherosclerosis." (PMID 22984509, 2012). "Exercise also increases ABCA1 expression in macrophages, promoting reverse cholesterol transport, raising HDL levels, thereby reducing atherosclerosis risk." (PMID 41515269, 2026). "Mutations in the ABCA1 gene result in extremely low levels of HDL, as in Tangier disease, which significantly increases the risk of atherosclerosis." (PMID 40943400, 2025). "PPARγ exerts anti-atherosclerosis effects by promoting the removal of cholesterol from macrophages via cholesterol transporters such as ABCA1 protein." (PMID 41464973, 2025). "This study establishes Listerin as a protective factor in atherosclerosis via posttranslational stabilization of ABCA1, offering a potential therapeutic strategy targeting ABCA1 ubiquitination to enhance cholesterol efflux." (PMID 40526435, 2025). "In atherosclerosis, the expression of ABCA1 and ABCG1 is decreased, which aggravates the accumulation of cholesterol and formation of foam cells." (PMID 38600398, 2025). "KLF14 further contributes to lipid metabolism regulation by enhancing cholesterol efflux via ABCA1, highlighting the multifaceted involvement of KLFs in atherosclerosis pathogenesis." (PMID 41373858, 2025).
atherosclerosis (continued). "In the context of CS, pathways such as antigen processing and presentation, NK cell-mediated cytotoxicity, lipids, and atherosclerosis were activated, with increased ABCA1 expression." (PMID 40264650, 2025). "Considering the pivotal role of metabolic imbalance in cholesterol as a constituent cause of atherosclerosis, we investigated the concentrations of proteins affiliated with cholesterol absorption and discharge, inclusive of CD36, SR‐A1, ABCA1, and ABCG1." (PMID 39804798, 2025). "This study aimed to explore the effects of red watermelon extract on the expression of PCSK9, LOX-1, ROS, TNFα, CD36, and ABCA1 in a Wistar rat model of atherosclerosis." (PMID 40699832, 2025). "In contrast, ABCA1 regulates cholesterol efflux from the macrophages to HDL particles, which clear cholesterol from the macrophages and reduce the risk of atherosclerosis." (PMID 40699832, 2025). "The next critical step in understanding the pathophysiology of atherosclerosis involves characterizing the precise structural and functional consequences of oxidative stress on ABCA1 and ABCG1." (PMID 41300518, 2025). "IMM-H007 reduced atherosclerosis development by suppressing ABCA1 degradation in preclinical trials." (PMID 40176913, 2025). "In the progression of atherosclerosis, ABCA1 and ABCG1 play critical roles in mediating cholesterol efflux from macrophages to HDL." (PMID 38600398, 2025). "The mRNA and protein expression of TGF-β, PPAR-γ, LXR-α, and ABCA1 in aortic and liver of atherosclerosis apoE−/− mice were upregulated (p < 0.05, p < 0.01), while those of PI3K and Akt1 were suppressed (p < 0.05, p < 0.01)." (PMID 41464973, 2025). "Deficiency of ABCA1 and ABCG1 in macrophages increases inflammation and accelerates atherosclerosis." (PMID 41252867, 2025). "Path analysis demonstrates the interrelationships of Citrullus lanatus (CL), PCSK9, LOX-1, CD36, ABCA1, and foam cell (FC) formation in atherosclerosis." (PMID 40699832, 2025). "This protective effect is achieved through the activation of the AMPK/ABCA1 and Krüppel-like Factor 2 pathways, thereby slowing the progression of atherosclerosis." (PMID 40649729, 2025). "In summary, our study demonstrates that the macrophage Listerin has an important effect on the pathogenesis of atherosclerosis, an effect different from that seen in yeast and bacteria, and reveals another regulatory mechanism of ABCA1." (PMID 40526435, 2025). "Macrophage ABCA1 degradation leads to lipid deposition and foam formation in macrophages, promoting the development of atherosclerosis." (PMID 40526435, 2025). "Increased pathways involved in lipids and atherosclerosis likely relate to the formation of foam cells (e.g. genes Olr1, Abca1, and Abcg1)." (PMID 40513100, 2025). "This study was conducted to explore how red watermelon (Citrullus lanatus) consumption modulates the lipid profile, and the expression of PCSK9, LOX-1, CD36, ROS, TNFα, and ABCA1 so that it can inhibit the development of atherosclerosis." (PMID 40699832, 2025). "In macrophages, CXCL12 has been proven to inhibit ABCA1‐dependent cholesterol efflux and aggravate atherosclerosis." (PMID 39763069, 2025). "This further silences the transcription and expression of ABCA1, reduces intracellular cholesterol efflux, and promotes intracellular lipid accumulation and the progression of atherosclerosis." (PMID 41303341, 2025). "Macrophage cholesterol efflux, facilitated by ABCA1, plays a pivotal role in alleviating lipid accumulation and atherosclerosis development, making ABCA1 and macrophage cholesterol efflux as primary targets for preventing and treating atherosclerosis." (PMID 39010173, 2024).
atherosclerosis (continued). "This study aimed to evaluate the therapeutic potential of tetrandrine in high cholesterol diet (HCD)-induced atherosclerosis, in rats, via modulation of miR-34a, as well as, Wnt5a/Ror2/ABCA1/NF-κB pathway and to compare its efficacy with atorvastatin." (PMID 39266573, 2024). "The literature highlighted the role of Wnt5a/Ror-2/ABCA1/NF-κB in the pathogenesis of atherosclerosis." (PMID 39266573, 2024). "CGA (400 mg/kg/day) can decrease the lesional areas of atherosclerosis in ApoE−/− mice by activating the PPARγ–liver X receptor α (LXRα)–ATP-binding cassette transporter A1 (ABCA1) signaling." (PMID 38612964, 2024). "Other studies have shown that the inhibition of miR-33-5p in mice with atherosclerosis leads to a significant increase in ABCA1 expression, promoting the reverse transport of cholesterol and the reduction of atherosclerotic injury." (PMID 39201292, 2024). "This established a significant association between ABCA1 and CXCL12 gene expressions with atherosclerosis, partly influenced by HIV." (PMID 39483879, 2024). "LncRNA Mexis promotes the transcription of Abca1 in macrophages, which gene participates in the production of high-density lipoprotein in atherosclerosis and promotes cholesterol efflux." (PMID 38347610, 2024). "Studies have shown that AMPK prevented the development of atherosclerosis-related cardiovascular disease by upregulating the expression of ABCA1 and ABCG1 in macrophages and promoting HDL-regulated cholesterol efflux in macrophages." (PMID 38999750, 2024). "MiR-33a-5p ablation de-represses ABCA1 and promotes cholesterol efflux in macrophages, which impedes atherosclerosis progression in mice." (PMID 39765632, 2024). "The inflammatory corpuscle recombinant absents in melanoma 2 (AIM2) and cholesterol efflux protein ATP binding cassette transporter A1(ABCA1) have been reported to play opposing roles in atherosclerosis (AS) plaques." (PMID 38734775, 2024). "The QiShenYiQi pill hinders atherosclerosis by stimulating cholesterol retrogradation through the PPARγ-LXRα/β-ABCA1 pathway, consequently diminishing lipid deposition." (PMID 38952541, 2024). "They illustrated an increase in the miR-34a expression level in atherosclerosis leads to decrease in the ABCA1 level leading to vicious cycle between hyperlipidemia, oxidative stress and inflammatory conditions." (PMID 39266573, 2024). "Stable overexpression of MeXis in macrophages boosts ABCA1 expression, leading to more effective cholesterol elimination and considerably decreasing the likelihood of atherosclerosis." (PMID 39273193, 2024). "Specifically, bone marrow-recipient mice with Abca1 and Abcg1 knockout mice exhibited accelerated atherosclerosis and extensive infiltration of the myocardium and spleen with foamy cell macrophages." (PMID 39857239, 2024). "Deficiency of HDAC9 promotes cholesterol efflux from macrophages and reduces plaque area in atherosclerosis‐prone mice by enhancing the expression of ABCA1 and ABCG1." (PMID 39698913, 2024). "Mutations in ABCA1 can lead to a severe deficiency in high-density lipoprotein (HDL), causing cholesterol buildup in tissue macrophages and promoting atherosclerosis." (PMID 38673936, 2024). "Specifically, we reported that Cullin 3, an E3 ubiquitin ligase, ubiquitinates and degrades ABCA1 in promoting diet-induced atherosclerosis." (PMID 38537695, 2024). "This highlights the ability of tetrandrine to ameliorate atherosclerosis in rats via modulating miR-34a as well as Wnt5a/Ror-2/ABCA1/ NF-κB pathway." (PMID 39266573, 2024). "Significantly diminished ABCA1 expression in macrophages translated into exacerbated progression of atherosclerosis." (PMID 39273193, 2024). "AI662270 accelerates the progression of atherosclerosis by directly binding to Abca1 to attenuate Abca1 expression and activity and inhibiting SR-BI expression to promote foam cell formation." (PMID 38715092, 2024).
atherosclerosis (continued). "CK also regulates the reverse transport of cholesterol and promotes the ATP-binding cassette transporter A1 (ABCA1), resulting in a reduction in total cholesterol in the blood, blood viscosity, and relieving atherosclerosis." (PMID 37511939, 2023). "The main mechanisms of chlorogenic acid in inhibiting atherosclerosis include increased synthesis and mRNA expression of PPARγ, LXRα, ABCA1 and ABCG1, as well as transcriptional activity resulting from PPARγ activation." (PMID 37432383, 2023). "ABCA1 and ABCG1 deficiency increases foam cell formation and accelerates the development of atherosclerosis in mice." (PMID 37324843, 2023). "Consistent with expectations, animal models have demonstrated that lncRNAs promoting ABCA1 expression alleviate atherosclerosis, whereas those suppressing ABCA1 expression exacerbate its progression." (PMID 37509544, 2023). "Collectively, MP is a direct agonist of AMPK and a promising candidate molecule for strengthening ABCA1 stability, increasing macrophage cholesterol efflux, and preventing atherosclerosis." (PMID 38139111, 2023). "Heat shock protein 70 (HSP70) accelerates atherosclerosis by downregulating the expression of ABCA1 and ABCG1 through the JNK signaling pathway." (PMID 37021059, 2023). "Because regulation of cholesterol efflux is crucial for the prevention of atherosclerosis, ABCA1 has been one of the primary targets in lncRNA research." (PMID 37509544, 2023). "A traditional Chinese medicine Yin‐xing‐tong‐mai decoction (YXTMD) has been used to treat atherosclerosis by activating the PPARγ‐LXRα‐ABCA1/ABCG1 pathway to enhance cholesterol efflux." (PMID 37324843, 2023). "Increased SMAD1 expression leads to decreased levels of the cholesterol transporters ABCA1 and ABCG1, with lipid accumulation by macrophages producing foam cells that are associated with atherosclerosis." (PMID 37164635, 2023). "Interventional and genetic studies, as well as research using gene manipulation techniques, have determined the inhibitory effect of ABCA1/G1-mediated macrophages’ cholesterol efflux on foam cell formation and atherosclerosis." (PMID 37432260, 2023). "For example, betulin can reduce atherosclerosis by upregulating ABCA1 and ABCG1 expression 39 or inhibiting the degradation of ABCA140." (PMID 36923537, 2023). "Regarding most classical mechanisms of atherosclerosis, miR-155 has been related to cholesterol efflux mediated by ABCA1/ABCG1, which is a key process in macrophage foam cell formation." (PMID 37275892, 2023). "PRMT2 represents a glucose-sensitive factor controlling ABCA1-dependent cholesterol efflux, while it has potential to explain atherosclerosis in diabetic patients." (PMID 37144154, 2023). "Our findings indicate that the novel lncRNA AI662270 can interact with anti-atherosclerotic protein Abca1 to aggravate atherosclerosis." (PMID 36755320, 2023). "PPARγ agonists or activators can promote macrophage cholesterol efflux and protect against atherosclerosis by augmenting the expression of LXRα and ABCA1/G1." (PMID 36713845, 2023). "The ATP-binding cassette transporter 1 (ABCA1) is a membrane protein that mediates the extracellular transport of cholesterol and phospholipids, having a protective role against atherosclerosis." (PMID 37510094, 2023). "Previous studies from our laboratory and others have shown that ABCA1 promoted cholesterol efflux to suppress foam cell formation and atherosclerosis development 121-125." (PMID 37324939, 2023). "Together, these results indicate that AI662270 aggravates atherosclerosis, at least partially, by impairing the function of Abca1 and inhibiting the SR-BI expression." (PMID 36755320, 2023). "The animal experiment results suggested that CKN can effectively prevent the development of atherosclerosis in ApoE−/− mice by upregulating ABCA1 expression in macrophages." (PMID 37322486, 2023).